HLA-G (major histocompatibility complex, class I, G)
Diseases named in the same sentence as HLA-G in open-access papers (continued):
Sharing a sentence is not in itself a finding about the gene and the disease.
tumor (continued). "Next to HLA-G and PD-L1 (B7-H1) in silico analyses of RCC TCGA data also identified B7-H3, B7-H5, HVEM, CD40, CD70 and ILT2 (on tumor cells) as putative novel ICP axes." (PMID 35185904, 2022). "Decitabine treatment increased HLA-G expression in tumor cells and enhanced recognition of these cells by specific CD4+ helper T lymphocytes, suggesting a combination of decitabine with HLA-G targeting to improve T cell-based immunotherapy." (PMID 35203421, 2022). "The combined high expression of HLA-G and IDO, along with HLA-E, correlated with tumor size and invasion depth." (PMID 35328349, 2022). "In addition, since HLA-G, either soluble or present on the surface of tumor-derived EV, is able to up-regulate PD-1 expression on T lymphocytes upon interaction with ILT2, it is tempting to speculate that the inhibition of this pathway may restore T cell cytotoxic activities against tumor cells." (PMID 35328349, 2022). "HLA-G engagement of its cognate receptors, ILT-2, ILT-4 and KIR2DL4 expressed on immune cells, can significantly induce immunosuppression and result in tumor immune escape." (PMID 35185887, 2022). "HLA-G is frequently, but heterogeneously expressed in both RCC and BC, which is dependent on the tumor subtype, tumor grading or staging as well as the composition of the immune cell infiltration." (PMID 35185904, 2022). "Because PD1/PDL1 and HLA-G/ILT2 seem to work as independent mechanisms, a combination of therapies would cover a wider range of cells to restore the anti-tumor activity of the immune system." (PMID 35154112, 2022). "In addition to its localization and physiological function, HLA-G expression has been observed in different types of tumors, such as gastric, colorectal and breast cancer, among others, where it favors tumor progression by inhibiting the immune system surveillance." (PMID 35154112, 2022). "HLA-G has an impact on the clinical course of persistent HPV infections, epithelial cell transformation, tumor growth, metastasis, formation and therapy resistance." (PMID 35237271, 2022). "HLA-G exerts its function through its binding to immunoglobulin-like transcript 2 (ILT2) and KIRs on NK cells to protect tumor cells from NK cell cytotoxicity." (PMID 36560427, 2022). "Several studies have demonstrated that the binding of HLA-G expressed on tumor cells to immune cells bearing ILT-2 and ILT-4 aids the evasion of the anti-tumor immune responses of the host." (PMID 34054869, 2021). "HLA-G/ILT-2/-4 (HLA-G/ILTs) signaling can drive comprehensive immune suppression, promote tumor growth and disease progression." (PMID 34276691, 2021). "HLA-G can inhibit the activities of all immune cells by interacting with its receptors ILT2 and ILT4, thus protecting tumor cells from host antitumour responses." (PMID 34276642, 2021). "Moreover, elevated levels of human leucocyte antigen-G (HLA-G) in CC may inactivate the local immune system, thus altering the tumor microenvironment as well as promoting proliferative and metastatic capability of the tumor." (PMID 34204445, 2021). "Therefore, until it becomes possible to make a distinction between the different HLA-G isoforms and determine the proportions wherein distinct HLA-G isoforms are presented within the tumour lesion, it remains uncertain what the exact role of specific HLA-G isoforms is in different tumour types." (PMID 34361031, 2021). "However, the interaction of HLA‐G expressed by tumor cells and ILT2 could significantly inhibit the effector function of TILs, and ILT2 blockade could rescue this inhibition, indicating the possibility of the combination of HLA‐G/ILT2 blockade and PD‐1/PD‐L1 blockade." (PMID 34382349, 2021). "We also identified subgroup‐specific differences: TIF‐1γ+ patients showed upregulation of HLA‐G, HLA‐DQA1, and BAGE, the latter being a well‐known tumor antigen present in many cancers." (PMID 34043263, 2021).
tumor (continued). "We then analyzed the expression of immune checkpoint proteins, HLA-G, ILT-2, ILT-4, and PD-L1, using multicolor flow cytometry in EpCAM+-gated tumor cells from frozen CRC samples." (PMID 34054869, 2021). "In this regard, targeting multiple checkpoints, especially potential antagonists of the HLA-G/ILT-2/4 pathway, is urgently needed to target the entire tumor." (PMID 32670296, 2020). "HLA-G expression was correlated with advanced stages of the “tumor-node-metastasis” (TNM) classification and a diminution of the survival rate (<3 years) for HLA-G positive patients." (PMID 32922387, 2020). "Consistent with this, the results also revealed the inverse relationship among HLA-G expression levels and estimated numbers of tumor infiltrating lymphocytes (TILs) and CD57+ NK cells, which favors an escape from host anti-tumor activity." (PMID 32670296, 2020). "Of note, HLA-G belongs to the immunosuppressive factors secreted by the TME components in hematological malignancies, which contributes to the immune evasion of tumor cells." (PMID 32610578, 2020). "Therefore, HLA-G could profoundly alter the phenotype and functional activity of immune cells, and thus may be involved in regulating multiple aspects of the immune response during tumor development." (PMID 33425752, 2020). "In this context, the aim of this study is to explore the relationship between the immune checkpoint HLA-G/ILT4 and tumor angiogenesis based on the expression of VEGF-A and VEGF-C." (PMID 32620162, 2020). "As reviewed above, HOTAIR upregulates the expression of HLA-G in tumor tissues, which indicated the potential role of HOTAIR as a biomarker of tumor immune escape." (PMID 32083005, 2020). "In the tumor cells, some oncogenic lncRNAs regulate the immunogenicity of tumors by upregulating the expression of immune checkpoints (e.g., PD-L1 and IDO) and HLA-G, or directly by downregulating the generation of tumor antigens." (PMID 32083005, 2020). "Considering the role of both HLA-G and HPV in tumor growth and progression, it is pertinent to investigate the relationship between HLA-G and HPV in context of immune modulation in HNSCC." (PMID 30859089, 2019). "HLA-G is an immunoregulatory class I MHC molecule that have been found to be expressed by decidual trophoblasts and in diverse tumor tissues." (PMID 30939820, 2019). "SOCS are reported to have anti-tumor activity and also SOCS and soluble HLA-G are known to interfere with cell cycle progression." (PMID 30859089, 2019). "Nevertheless, recent discoveries showing that hypoxia negatively impacts the tumor immune response by modifying the expression of main immune checkpoints (e.g., PD-L1, CD47, PD-1, HLA-G...) provide a major opportunity for innovative combination approaches." (PMID 31540045, 2019). "HLA-G, an inhibitory ligand in GBM, is found to bind to its receptor Ig-like transcript 2 on NK cells, activating a major tumor-immune escape mechanism." (PMID 30619286, 2018). "The induced aberrant expression of HLA-G (membrane-bound and soluble) and increased shedding of MICA (sMICA) seen in tumor cells can further suppress NK-cell antitumor immune responses." (PMID 28377768, 2017). "HIF-1 in response to hypoxia acts as a negative or positive regulator of HLA-G depending on the type of cell line (HLA-G− or HLA-G+), highlighting the delicate balance mediated by HIF-1 during adaptation of tumor cells to hypoxic environment." (PMID 28781970, 2017). "NK cell anti-tumor activity in primary tumors can be further impeded by expression of non-classical MHC class I molecules such as human leukocyte antigen (HLA)-E and HLA-G on CRC cells." (PMID 27367680, 2016). "Recently, it has been reported that like tumor cells, unmanipulated MSC also express and secrete HLA-G that confers an advantage to the tumor." (PMID 26460949, 2015).
tumor (continued). "Due to all of these properties, HLA-G has been recognized as a tolerogenic molecule, and the tissue expression of HLA-G may protect or harm; that is, it may protect allografts against attack by the recipient immune system and may impair the cytotoxic immune response against tumor cells." (PMID 24741620, 2014). "The expression of HLA-G on blasts and the analysis of DC-10 and HLA-G+ CD4+ Tregs can be used to evaluate the effectiveness of anti-tumor therapies." (PMID 24741612, 2014). "Western blot analysis detected a specific band of 39 kDa which identifies the membrane-bound form of HLA-G in TL from three-weeks-old NKPSG cells and the M8-HLA-G1 tumor cell line used as positive control." (PMID 18493613, 2008). "In contrast, no response was seen in the patient with a mixed PSTT / epithelioid trophoblastic tumor (ETT) with > 90 % PD-L1 expression but lacking tumour-infiltrating lymphocytes and HLA-G expression." (PMID 41567618, 2026). "HLA-G, a non-classical human leukocyte antigen (HLA) molecule, primarily functions in immune regulation, with well-established roles in tumor immunity, pregnancy, and transplant immune tolerance." (PMID 40995515, 2025). "HLA-G transcript levels were significantly higher in malignant PCs compared to other BM cell populations (log2(TPM+1), p = 0.0416), supporting the protein-level data and reinforcing the immunosuppressive phenotype of tumor cells." (PMID 40948764, 2025). "Furthermore, LILRB2 can interact with HLA-G in the TME, promoting myeloid cell tumor proliferation and increasing tumor immune evasion." (PMID 41050411, 2025). "Together, these molecules form an integrated network of non-classical HLA-mediated immune checkpoints, with HLA-G at the center and HLA-E/HLA-F providing complementary mechanisms of immune modulation relevant to both tolerance and tumor escape." (PMID 41445738, 2025). "Different proportions and intensities of immune suppressor HLA-G expression have been frequently observed in various solid cancer lesions, while HLA-G is rarely expressed in tumor-adjacent non-tumorous tissues." (PMID 41181133, 2025). "Although the primary function of HLA-G is to inhibit the immune response, its interaction with ILT4 may also create a favorable microenvironment for tumor growth." (PMID 39766165, 2024). "Human leukocyte antigen-G (HLA-G) is a non-classical human HLA class I molecule, now considered an immune-checkpoint protein due to its role in tumor-driven immune escape mechanisms." (PMID 39703498, 2024). "Anti‐HLA‐G CAR‐T cell therapy can benefit even low or inconsistent HLA‐G expression, while engineering CAR‐T cells to produce scFv targeting PD‐1 enhances their ability to kill tumours and improves therapeutic outcomes in animal models." (PMID 39328262, 2024). "HLA-G is presumably the most distinct immunosuppressive molecule of the non-classical HLAs favoring tumor immune escape." (PMID 39766165, 2024). "Our data demonstrated a strong correlation between HLA-G expression on tumor cells and both overall survival and disease specific survival rates in MIBC patients, highlighting the clinical and biological significance of HLA-G in cancer progression and prognosis." (PMID 39469714, 2024). "No activity was observed against cancer cells lacking HLA-G membrane expression, underscoring its specificity for antigen-expressing tumor cells." (PMID 39105878, 2024). "The neoplastic environment appears to become progressively more immunosuppressed and immunotolerant as the tumor advances, with a strong positive influence among the immunoinhibitory molecules PD-L1, PD-L2 and HLA-G in the non-operated on group." (PMID 38954689, 2024). "The results showed that the expression levels of PD‐L1 and HLA‐G in advanced NSCLC tumors were higher than those in early‐stage tumors, with no detectable expression observed in the paired normal tissue adjacent to the tumor (NAT)." (PMID 39234811, 2024).
tumor (continued). "For instance, in NK cells, interaction of HLA-G and LILRB1 was shown to counteract signaling and induction of cytotoxicity by interaction of the activating NK cell receptor NKG2D with its ligand MIC A on tumor cells." (PMID 37781391, 2023). "The tolerogenic nonclassic HLA-G, acquired from tumor cells can convert effector T cells into induced regulatory T cells (iTreg)." (PMID 37974170, 2023). "Subsequently, HLA-G expression has been detected in various tumor tissues but is typically absent in surrounding healthy tissues." (PMID 37627278, 2023). "Recently, the first anti-HLA-G chimeric antigen receptor (CAR)-T cells targeting HLA-G, which is both a tumour-specific antigen and an immune checkpoint molecule, could specifically target and eliminate both tumour cells and HLA-G+-suppressive cells." (PMID 36053326, 2023). "HLA-G and BRAF tumor expression was evaluated by immunohistochemistry." (PMID 37569841, 2023). "HLA-G expression and inhibitory cytokines’ secretion may promote local immunosuppression tumour microenvironment, which favours HPV persistence and tumour transformation." (PMID 36053326, 2023). "Hypoxia modulates PD-L1, human leukocyte antigen g (HLA-G), CD47, and the immune checkpoint V-domain IG suppressor of T cell activation (VISTA) to form an inhibitory immune microenvironment, promoting immune escape of tumor cells." (PMID 36212414, 2022). "The HLA-G-positive cancer cells were primarily located in the invasive margin or in the deeper compartments of the tumour (data not shown)." (PMID 35027037, 2022). "Due to its immunosuppressive activity, the negative role of HLA-G has been found to be related to the development of the tumor process." (PMID 35626255, 2022). "For instance, HLA-G and HLA-E, the non-classical MHC-I molecules implicated in the protective maternal-fetal barrier in the placenta, are highly upregulated on tumor and myeloid cells in the EwS TME." (PMID 36612267, 2022). "HLA-G might be a valid target for CAR-T cell therapy to specifically target and eliminate both tumor cells and HLA-G." (PMID 36380313, 2022). "As the IL-1β free environment allows tumor cells to escape maternal immune control, these cells undergo camouflage through an increase in the expression of a selected repertoire of proteins that includes check point proteins such as PDL1; HLAG and βhCG." (PMID 35203462, 2022). "A strong intratumoral heterogeneity exists in RCC for the expression of ICPs, such as PD-L1, B7-H3, PD-L2 and HLA-G, in primary RCC lesions with a highly variable HLA-G expression either between patients’ tumor samples or at different areas within a tumor tissue." (PMID 35185904, 2022). "Tumor immunohistochemistry revealed positive staining (over 90%) for PD-L1 and HLA-G and negative staining for HLA-A." (PMID 35681761, 2022). "Various mechanisms can be involved, including upregulation of inhibitory ligands and non-classical MHC class I molecules HLA-E and HLA-G on the tumour that suppress NK cell cytotoxicity and induce tumour tolerance." (PMID 35806034, 2022). "In addition, the finding that the anti-tumour effect of activated NK cells is restricted by HLA-ABC and HLA-G only in the 3D model proves its biological relevance." (PMID 35747143, 2022). "Notably, they revealed that low-dose chemotherapy-induced accumulation of HLA-G (involving suppression of DMNT1 and TAP-1 promoter demethylation) further improves the anti-tumor efficacy of HLA-G CAR NK cells." (PMID 36428748, 2022). "Since transferred HLA-G remains functional, the immune effector cells with acquired HLA-G on their surface do not attack the tumor cells and even gain the capability to inhibit other immune effector cells." (PMID 35185904, 2022). "HLA-G is also expressed on hematological malignancies, although a connection between expression and tumor growth has not been established." (PMID 35865547, 2022).
tumor (continued). "Since tumor-derived HMGB-1 may inhibit anti-tumor T cell responses through the ligation of TIM-3 on T cells and the up-regulation of HLA-G on tumor cells, an inhibitor of HMGB-1 may be tested in combination with anti-HLA-G antibodies." (PMID 35328349, 2022). "HLA-G, a non-classical HLA molecule, physiologically involved in tolerogenic mechanisms, has recently emerged as a relevant prognostic marker in other tumor types, but ambiguous data are reported in the CRC setting." (PMID 35902421, 2022). "The interaction of these IC molecules and their ligands with HLA-G/ILT2 axis may be relevant for the induction of a tolerogenic microenvironment, which in turn leads to the escape of tumor cells from the control of the immune system." (PMID 35328349, 2022). "Suppressive molecules contained in tumor-derived EV or expressed on EV membrane included cytokines and chemokines, ligands for inhibitory receptors (i.e., PVR, PD-L1, FasL, MIC A/B), miRNAs, HLA-G and adenosinergic ectoenzymes." (PMID 33921337, 2021). "We conclude that negative effects on immune effector cells in the TME of HLA-G-positive tumors can be mediated by myeloid bystander cells rather than by direct interactions between HLA-G expressing tumor cells and CART." (PMID 34201079, 2021). "Several studies showed that NB metastatic cells express distinctive features from primary tumor cells, including down-regulation of several tumor suppressor genes (i.e., SIRT6, BBC3/PUMA, STK11, CADM4 and GLTSCR2) and up-regulation of immunosuppressive molecules, such as calprotectin and HLA-G." (PMID 33921337, 2021). "While the role of KIR2DL4 in the NK cells in the tumor microenvironment remains uncharacterized, we found that, in the absence of HLA-G, KIR2DL4 forms a feedback circuit with IFN-γ to promote trastuzumab-induced ADCC in vitro." (PMID 34158475, 2021). "This implies that tumour HLA-G expression is not necessarily part of an inhibited tumour-immune response and tumour progression." (PMID 34361031, 2021). "Further growth in situ of this initial tumor would require implantation in the host and vascularization through the overexpression of some aspecific checkpoint molecules, such as CD44, ID, LIF, HSP70, and HLA-G." (PMID 34295890, 2021). "The precise distribution of HLA-G-positive samples across the various staining intensities was not mentioned and it was unclear when tumour samples were considered HLA-G positive." (PMID 34361031, 2021). "HLA-G induces IL-6 production and, thus, the activation of the gp130–JAK–STAT3 pathway, regulating proliferation, migration, invasion, and angiogenesis, namely, tumor progression and metastasis." (PMID 34295890, 2021). "All three studies used different HLA-G-detecting mAbs and quantification methods, but no major deviations in the percentage of HLA-G-positive tumour samples were observed, ranging from 59–71%." (PMID 34361031, 2021). "In previous work in EwS, we found that tumor xenografts in response to adoptive therapy with GD2-redirected CAR NK cells or CART strongly upregulate the nonclassical MHC class I molecule HLA-G." (PMID 34201079, 2021). "HLA-G, which binds to CD85j with higher affinity than the classical MHC-I, is expressed in RCC cells and plays an inhibitory role on NK cell-mediated cytotoxicity against tumor cells." (PMID 34149719, 2021). "Abnormal expression of HLA-G was significantly correlated with the pathological stage of some but not all tumor types." (PMID 34276642, 2021). "We observed a significant difference between the high and low HLA-G expression groups in overall survival (OS) or disease-free survival (DFS) in some but not all tumor types." (PMID 34276642, 2021). "The second edited tumor cell line was JEG-3, which naturally expresses high levels of HLA-G." (PMID 34773056, 2021). "Other strategies of the tumor cells to escape the immune surveillance are the downregulation of MHC class I molecules or upregulation of non-classical HLA-G." (PMID 34680337, 2021).